SMARCA4 (SWI/SNF related BAF chromatin remodeling complex subunit ATPase 4)
Diseases named in the same sentence as SMARCA4 in open-access papers (continued):
Sharing a sentence is not in itself a finding about the gene and the disease.
lung carcinoma (continued). "While gastrointestinal metastases from primary lung cancer are uncommon (0.2% to 2.0%), a previous report has documented small intestine metastasis in SMARCA4-UT, suggesting this pattern may be more characteristic than previously recognized." (PMID 39360100, 2024). "CDK4/6 inhibition is synthetic lethal in SMARCA4-mutant lung cancer." (PMID 39345502, 2024). "In summary, our study identified ROCK kinases as critical mediators of metabolic adaptation of cancer cells to OXPHOS inhibition and provides a strong preclinical basis for pursuing ROCK inhibitors as novel combination partners to OXPHOS inhibitors in SMARCA4-mutant lung cancer treatment." (PMID 39345502, 2024). "Impact of SMARCA4 on ICIs treatment outcomes for patients with lung cancer." (PMID 39322625, 2024). "SMARCA4-mutant lung cancer cells with intact SMARCA2 depend on elevated OXPHOS activity by upregulating the master transcription factor PGC-1a38, whereas ARID1A inactivation in ovarian cancer cells causes reliance on glutamine metabolism through activating glutaminase expression." (PMID 37210563, 2023). "However, SMARCA4 has also been shown to be a tumor suppressor in various cancers, including lung cancer, colorectal cancer, and pancreatic cancer." (PMID 36902184, 2023). "SMARCA4 is considered to play a critical role in cell growth arrest and cellular senescence and is hypothesized to be a tumor suppressor gene in lung cancer." (PMID 37664030, 2023). "We selected 105 patients with SMARCA4‐dNSCLC and 221 patients with SMARCA4‐intact non‐small cell lung cancer (SMARCA4‐iNSCLC) by performing immunohistochemical analysis of 1520 NSCLC samples, and we assessed the patients' clinicopathological features and survival state." (PMID 37184108, 2023). "SMARCA4 was essential for immune response, and the presence of a SMARCA4 alteration may confer a worse outcome to immunotherapy among lung cancer." (PMID 35664743, 2022). "Furthermore, a novel small molecule, namely IACS-010759, which is an inhibitor of OXPHOS undergoing clinical development, showed a potent antitumor efficacy in SMARCA4-mutant lung cancers." (PMID 36361605, 2022). "Validation was performed using an independent transcriptome dataset including SMARCA4-UT, non–small cell lung cancers (NSCLC) with/without SMARCA4 mutations, and unclassified thoracic sarcomas (UTS)." (PMID 35278076, 2022). "However, Futreal and colleagues have shown that SMARCA4 acts as a tumor suppressor by directing a transcriptional program that steers lung cancer cells away from drawing energy from oxidative phosphorylation." (PMID 33853662, 2021). "We tested the effects of GSK-J4 on the growth of our panel of cancer cells and found that the drug was more toxic in the SMARCA4def cells, with a five-fold lower EC50 than in the MYCamp cells or in the lung cancer cells that are wild type for both SMARCA4 and MYC." (PMID 34262032, 2021). "In this case, the immunodetection of SMARCA4 serves to distinguish between thoracic sarcomas and lung carcinomas, as the latter usually do not display a loss of SMARCA4 nuclear expression." (PMID 34771683, 2021). "SMARCA4-mutant lung cancers may be more sensitive to immunotherapy, but other studies have contradictory results." (PMID 34675941, 2021). "However, so far, only SMARCA4-mutant tumors have been the target of synthetic lethal therapies in lung cancer." (PMID 33321963, 2020). "Here, we investigated this synthetic lethal interaction in SMARCA4-deficient NSCLC, which has a complex mutation landscape, and explored the potential strategy of using CDK4/6 inhibitors to treat this highly aggressive subgroup of lung cancer." (PMID 30718506, 2019).
lung carcinoma (continued). "The SMARCA4 protein was immunohistochemically lost in both SCCOHTs and the lung carcinoma." (PMID 27866340, 2017). "Consequently, we investigated the correlation between SMARCA4 mutations and disease progression in lung cancer patients, given the absence of genetic sequencing data for SMARCA4‐deficient undifferentiated thoracic tumors." (PMID 41577374, 2026). "Non–small cell lung cancer harboring a SMARCA4/SMARCA2 deficiency has no established treatment because it is mutually exclusive to genetic abnormalities such as EGFR mutations and anaplastic lymphoma kinase (ALK) and RET fusions, for which there are established treatments." (PMID 39625239, 2025). "Furthermore, all the SMARCA4-deficient lung cancer cell lines localising to this SMARCA4-UT cluster showed a gene expression profile characteristic of SMARCA4-UT, which was distinct from that of SCLC and SMARCA4-mutant NSCLC." (PMID 38180245, 2024). "In lung cancer, mutations in the chromatin remodeling complex SWI/SNF, such as the genes SWI/SNF Related, matrix associated actin dependent regulator of chromatin, subfamily A, member 4 (SMARCA4) and AT‐rich interactive domain‐containing protein 1A (ARID1A), sensitize cells to OXPHOS metabolism." (PMID 38214418, 2024). "Indeed, treatment with a selective glutaminase inhibitor CB-83954 strongly suppressed cell viability and proliferation, reduced OXPHOS, and induced apoptosis in SMARCA4/2-deficient ovarian and lung cancer cell lines, but not in proficient controls." (PMID 37210563, 2023). "Despite overall inhibition of CDK4/6 has not been shown to be effective in lung cancer, it is possible the subset of patients with a SMARCA4 mutation may be more sensitive to CDK4/6 inhibitors." (PMID 37345003, 2023). "Notably, higher SLC38A2 expression is associated with poor survival in lung cancer patients whose tumors exhibited SMARCA4 deletion, but not in patients whose tumors did not harbor SMARCA4 alterations." (PMID 37210563, 2023). "However, for the lung cancer samples, we did not observe any significant association of SMARCA4-d with subtype (p = 0.72 for HMF; p = 0.65 for PCAWG; Fisher’s exact test)." (PMID 36883553, 2023). "This resulted in compound 6, a fast and potent dual degrader of SMARCA2/4 (SMARCA2 DC50 = 2 nM, Dmax = 77%; SMARCA4 DC50 = 5 nM, Dmax = 86%, in RKO cells after 4 h) that displayed the expected anti-proliferative effect (EC50 = 2 nM) in a SMARCA4-deficient lung cancer cell line, NCI-H1568." (PMID 36216795, 2022). "However, lung carcinomas, such as NSCLC, primary adenocarcinomas, and squamous cell carcinomas, are represented by a combination of an epigenetic silencing mutation of the SMARCA4 gene and SMARCA2 gene, which are primarily located at the chromosome 9p24.3, which encodes the BRM protein." (PMID 34440689, 2021). "We analyzed our previous single-cell RNA-seq (scRNA-seq) dataset from four lung cancer cell lines with differential LKB1 and SMARCA4 expression status to identify genes regulated by both LKB1 and SMARCA4." (PMID 41924094, 2026). "Additionally, SMARCA4 mutations are recognized as a genetic factor associated with poor clinical outcomes in lung cancer, regardless of whether patients undergo immunotherapy or non-immunotherapy treatments." (PMID 40416876, 2025). "It was also eminent that SMARCA4 plays a role in growth and tumorigenicity of KRAS-driven lung cancers by supporting the oncogenic transcriptional signaling landscape of the tumor." (PMID 34440689, 2021). "They reported that SMARCA4 interacted with Sp1 to activate LTBP2 transcription, thus promoting lung cancer progression." (PMID 33853662, 2021). "Studies have shown that inactivation of SMARCA4 promotes the invasion of NSCLC by altering chromatin organization, while decreased expression of SMARCA4 results in a poor prognosis of lung cancer." (PMID 35070984, 2021).
lung carcinoma (continued). "SMARCA4-mutant lung cancer accounts for approximately 10% of non-small-cell lung cancers (NSCLCs), has few effective treatments, and has been associated with a poor prognosis." (PMID 37214462, 2023). "In keeping with the fact that lung cancer cells have more complex genetic landscapes than SCCOHT15,62, only four genes, namely ITPR3, MATN2, EHD4, and ATP2B4, were consistently upregulated by SMARCA4 in both cancer types." (PMID 34518526, 2021). "To further validate our findings of ITPR3 regulation by SMARCA4/2 in cell models with genetic perturbation, we analyzed mRNA expression of ITPR3 and SMARCA4/2 in RNA-seq data sets of ovarian (n = 47) and lung cancer (n = 192) cell lines available from CCLE41,42." (PMID 34518526, 2021). "SMARCA2 and SMARCA4 deficiency was noted in 10% of nonsmall cell lung cancer cases, 80% of SMARCA2/SMARCA4 deficient tumors was also TTF-1 negative, and recently SMARCA4 loss was found to be a predictor of response to platinum based chemotherapy." (PMID 31093468, 2018). "In addition, SMARCA4/2 deletion reduces the expression of the Ca2+ channel IP3R3, which impairs the transfer of Ca2+ from the endoplasmic reticulum to the mitochondria required to induce apoptosis, leading to cisplatin resistance in ovarian and lung cancer." (PMID 39697230, 2024). "Extending on our above findings, in DepMap RNA-seq datasets of ovarian and lung cancer cell line panels, the expression of SLC2A1 mRNA significantly and positively correlated with that of SMARCA2 and SMARCA4 in cells with low (bottom quartile) SMARCA4 or SMARCA2 expression, respectively." (PMID 37210563, 2023). "As for the genetic landscape in detail, several incidences of mutated genes that were adverse to prognosis were observed to be lower in the young lung cancer group (LRP1B, SMARCA4, STK11, FAT2, RBM10, FANCM), which may explain the better prognosis of the young lung cancer group to some extent." (PMID 35096611, 2021). "Additionally, EGFR, MGA, SMARCA4, ATM, RBM10 and KDM5C which are lung cancer related genes are mutated only in LUAD but not in LUSC." (PMID 33672117, 2021). "As for the up-regulated or hypomethylated non-stability C-TSGs, some of them, such as SMARCA4 in the lung cancer, may be unknown stability C-TSGs." (PMID 23472150, 2013). "In particular, SMARCA4, ARID1A, and PBRM1 are lacking in 10% of lung cancer cases, 50% of ovarian clear cell carcinoma cases, and 40% of clear cell renal cell carcinoma cases, respectively." (PMID 39625239, 2025). "Histologically, they display undifferentiated features, lacking the typical cellular structure seen in other lung cancers, and are negative for epithelial markers such as epithelial membrane antigen (EMA) and pan‐cytokeratin (PCK), distinguishing them from SMARCA4‐NSCLC." (PMID 41577374, 2026).
non-small cell lung carcinoma (99 papers, 2013 to 2026). A group of at least three distinct histological types of lung cancer, including non-small cell squamous cell carcinoma, adenocarcinoma, and large cell carcinoma. "SMARCA4-deficient non-small cell lung cancer (SMARCA4-dNSCLC) is an aggressive malignancy with poor prognosis, rarely harboring EGFR, ALK, or ROS1 alterations." (PMID 41684594, 2026). "The designation was changed from SMARCA4-DTS to SMARCA4-UT, and the disease was categorized into two subtypes: SMARCA4-deficient undifferentiated thoracic tumors (SMARCA4-UT) and SMARCA4-deficient non-small cell lung cancer (SMARCA4-dNSCLC)." (PMID 41142791, 2025). "SMARCA4 mutations occur in almost all small cell carcinoma of the ovary hypercalcemic type and 8% of non-small cell lung cancer cases." (PMID 41170461, 2025). "Its deficiency constitutes a rare and aggressive subtype of non-small cell lung cancer (SMARCA4-DNSCLC) characterized by rapid progression, propensity for early metastatic dissemination, and dismal prognosis (median overall survival: ~6 months)." (PMID 41395620, 2025). "From a mechanistic perspective, SCCOHT is the most well-characterized of BRG1-null cancers, although SMARCA4 mutations also occur in up to 10% of non-small cell lung cancers sequenced." (PMID 40647552, 2025). "The disease shares overlapping features with the relatively more common SMARCA4-deficient non-small cell lung carcinoma (SMARCA4-dNSCC)." (PMID 40909976, 2025). "In particular, recent studies have reported that SMARCA4-deficient non-small cell lung cancers respond favorably to ICIs." (PMID 40866717, 2025). "SMARCA4-deficient non-small cell lung cancer (SMARCA4-dNSCLC) typically lacks target-driven gene alterations and are primarily resistant to cytotoxic drugs." (PMID 40313929, 2025). "Clinically, SMARCA4-deficient non-small cell lung carcinoma (SMARCA4-dNSCLC) were associated with the poorly differentiated histologic manifestations and poor prognosis." (PMID 40453096, 2025). "SMARCA4-deficient non-small cell lung cancer (NSCLC) represents a highly aggressive subtype with poor prognosis." (PMID 39465834, 2024). "Thoracic SMARCA4-deficient undifferentiated tumors represent a distinct entity from SMARCA4-deficient non-small cell lung carcinoma (NSCLC)." (PMID 39850892, 2024). "A 40-year-old male was newly diagnosed with SMARCA4-deficient undifferentiated non-small cell lung cancer." (PMID 38390699, 2024). "Another point to remember is distinguishing SMARCA4-UT from SMARCA4-deficient non-small cell lung cancer (SMARCA4-NSCLC), as the latter is relatively more prevalent." (PMID 38265099, 2024). "To date, there are only 2 globally documented instances of non-small cell lung cancer (NSCLC) with concurrent SMARCA4 deficiency and mutations in EGFR or ALK." (PMID 39465834, 2024). "In this context, a selective BRM inhibitor would be lethal to the ca. 10% of non-small-cell lung cancers (NSCLC) where the SMARCA4 gene is lost or mutated, but well tolerated in healthy tissue due to their unaltered expression." (PMID 38607017, 2024). "It requires differential diagnosis from other tumors, such as malignant rhabdoid tumor (MRT), small cell carcinoma of the ovary hypercalcemic type (SCCOHT), and SMARCA4-deficient non-small cell lung cancer (NSCLC)." (PMID 38903719, 2024). "SMARCA4-deficient non-small cell lung cancer predominantly affects male smokers aged 42 to 93 years and is characterized by high metastatic potential and poor prognosis." (PMID 39465834, 2024). "Studies have reported that ICI treatment is associated with a significantly improved prognosis in SMARCA4-abnormalized non-small cell lung cancer." (PMID 39697230, 2024). "In relation to cancer, it has been demonstrated in non-small cell lung cancer cells that SMARCA4 missense mutations in the ATPase domain similarly reduced nucleosome remodeling activity compared to the wild-type cells." (PMID 37433987, 2023).
non-small cell lung carcinoma (continued). "Here, we report on a 69-year-old male with heterogenous pathological presentations of SMARCA4-deficient non-small cell carcinoma." (PMID 37051241, 2023). "Thoracic SMARCA4-deficient undifferentiated tumor (SD-UT) is a highly aggressive disease that is nosologically related to but distinct from SMARCA4-deficient non-small cell lung cancer (SD-NSCLC)." (PMID 37115272, 2023). "In thoracic tumors, loss of SMARCA4 expression occurs in approximately 5% of non-small cell lung cancer (NSCLC) and was associated with more aggressive clinical behavior." (PMID 37115272, 2023). "Immunohistochemistry staining and genomic profiling confirmed the diagnosis of SMARCA4-deficient non-small cell carcinoma." (PMID 37051241, 2023). "Occasionally, there are cases that are less frequent and difficult to distinguish from SMARCA4-deficient non-small cell lung carcinoma (SMARCA4-dNSCLC)." (PMID 35151345, 2022). "SMARCA4-DTS is sometimes difficult to consistently distinguish from SMARCA4- deficient non-small cell lung carcinoma (SMARCA4-dNSCLC)." (PMID 35151345, 2022). "Potential targeted therapies, such as anti-PD-1 antibodies and CDK4/6 inhibitors, have been reported for treating SMARCA4-deficient non-small cell lung cancer (SMARCA4-deficient NSCLC)." (PMID 33836796, 2021). "Low expression of SMARCA4 has been associated with worse prognosis in patients with non-small-cell lung cancer." (PMID 35096557, 2021). "SMARCA4 inactivation is known to be associated with increased non-small cell lung cancer aggressiveness, which suggests that SMARCA4 functions as a tumor suppressor." (PMID 33853662, 2021). "The 19p CN-LOH associated with inactivating SMARCA4 mutations has also been reported in non-small cell lung cancer." (PMID 32575483, 2020). "Early preclinical studies suggested that SMARCA4-mutated tumors (such as non-small cell lung cancers) were critically reliant on the SMARCA2 paralog." (PMID 32575483, 2020). "EZH2 inhibitor treatment of non-small cell lung cancer cells bearing SMARCA4 mutations sensitizes these cells to chemotherapy, an effect that is not apparent in SMARCA4 wild-type cells." (PMID 31123059, 2019). "Mutations of SMARCA4 (BRG1) occur in 10–35% of non-small cell lung carcinoma, 15% of Burkitt’s lymphoma, 5–10% of childhood medulloblastoma, and less frequently in other cancers." (PMID 29298978, 2018). "Mutations in the SMARCA4/BRG1 gene resulting in complete loss of its protein (BRG1) occur frequently in non-small cell lung cancer (NSCLC) cells." (PMID 28102363, 2017). "Mutations in the SMARCA4 gene appear to be associated with various cancers including malignant melanoma, non-small cell lung cancer, head and neck and pancreatic cancer." (PMID 25886974, 2015). "Subsequently, mutations and/or loss of expression of the catalytic subunit SMARCA4 have been reported predominantly in non-small cell lung cancer (NSCLC), as well as other cancers." (PMID 25391308, 2014). "An interesting synthetic-lethality therapy principle involving the SWI/SNF catalytic subunit, BRG1/SMARCA4, frequently deficient in non-small-cell lung carcinomas by BRM-ATPase inhibitors targeting another SWI/SNF subunit, has been proposed in a recent study." (PMID 24036443, 2013). "This promotes tumorigenesis and development, manifesting as highly aggressive and metastatic characteristics with elevated tumor mutational burden, consistent with the aggressive phenotypes reported in SMARCA4-deficient tumors (e.g., non-small cell lung cancer, ovarian cancer)." (PMID 41395620, 2025). "SMARCA4 deficiency can be observed in a subset of non-small cell lung cancers (NSCLCs)." (PMID 38374950, 2024). "SMARCA4-deficient non-small cell lung cancer: Infiltrative poorly differentiated adenocarcinoma of the right lung with EGFR exon 21 L858R mutation, classified as stage IVB (cT3N2M1c) involving the right parietal lobe, right clavicle, and right sacroiliac joint." (PMID 39465834, 2024).